STAT3 (signal transducer and activator of transcription 3)
Diseases named in the same sentence as STAT3 in open-access papers (continued):
Sharing a sentence is not in itself a finding about the gene and the disease.
cancer (continued). "Furthermore, let-7 participates in the JAK2/STAT signaling pathway in cancer cells by targeting SOCS4 and activates the JAK1/STAT3 signaling pathway." (PMID 34568312, 2021). "The STAT3 N‐terminal and SH2 domains are potential targets for cancer therapy." (PMID 33382511, 2021). "Recent studies have revealed novel and diverse functions of STAT3 that are independent of its classic function in cancer." (PMID 33420372, 2021). "The exosomal Rab22a-NeoF1 fusion protein functions in its negative recipient cells, such as activation of RhoA and Stat3 in cancer cells and macrophages, respectively, which is dependent on its binding partner PYK2 from its positive donor cells." (PMID 33568623, 2021). "Moreover, PTP1B dephosphorylates the signal transducer and activator of transcription 3 (STAT3), which in turn increases C-C motif chemokine ligand 5 (CCL5) expression responsible for the invasion of cancer cells." (PMID 34638706, 2021). "Taken together, our study provides the impetus to discover new strategies, for instance, the development of efficient agents, including JAK2/STAT3 inhibitors and humanized monoclonal antibodies against IL6 to re-sensitize resistant NPC cells or other cancers that were resistant to chemotherapy." (PMID 34094941, 2021). "Consequently, the targets of STAT3, including NANOG, c-Jun, c-Myc, and BCL-XL, which played important roles in stemness of cancer, were also upregulated in RALYL-overexpressing cells." (PMID 33750796, 2021). "Thus, PTEN/PI3K/Akt, STAT3, and TIMP-3 represent major pathways that mediate the crosstalk between MetS and cancer." (PMID 34199293, 2021). "However, aberrant IL-6 mediated STAT3 signalling has been reported to suppress anti-cancer immunity in HCC, making the STAT3 signalling a target in cancer treatment." (PMID 34078370, 2021). "Since several studies have reported that RET activates STAT3 in different types of cancer, CDK5-mediated STAT3 activation with GDNF treatment remains unknown in this study." (PMID 34207842, 2021). "Furthermore, cytokines (IL-6 or tumor necrosis factor-alpha (TNF-α) trigger the NF-κB and STAT3 pathways, which are essential for enhancing FSCN1 expression in cancer." (PMID 34830909, 2021). "Acetyl-bufalin is a novel blocker of the CDK9/STAT3 pathway thus may have potential in therapy of NSCLC and other cancers." (PMID 33122847, 2021). "Our data collectively suggests that CXCR4/STAT3/Slug axis is paramount for IR resistance of NSCLC cells, and can be regarded as a therapeutic target to enhance the IR sensitivity of this devastating cancer." (PMID 33414415, 2021). "Evidence has also shown that STAT3 enables cross-talk of the JAK/STAT pathway with the other gp130/IL6ST-dependent pathways, contributing to cancer-promoting effects of the MAPK/MEK/ERK and PI3K/AKT signalling pathways, such as chemo-resistance and epithelial-mesenchymal transition (EMT)." (PMID 34834425, 2021). "STAT3 has also been shown to contribute to the effects of the hypoxia-inducible factor-1⍺ (HIF1⍺) transcription factor to promote angiogenesis, a key process in cancer progression and dissemination." (PMID 34834425, 2021). "Although STAT3 proteins are known to be ubiquitous in cells and found in the cytoplasm and mitochondrion, it is not known how the expression of STAT3 in different cancer cells can influence CT anticancer activity." (PMID 33544704, 2021). "Moreover, we revealed that the STAT3‐hnRNPA1 pathway participated in the process of miR‐27b‐3p packaging into exosomes, unveiling a novel mechanism of exosomal packaging in EMT cancer cells." (PMID 34936736, 2021). "STAT3, although perceived as a traditional target for treating cancer, until today, this is not translated into clinical usage." (PMID 34047814, 2021). "Upregulation of LRG1 in cancer cells relied on JAK2/STAT3 signaling, we hypothesized that LRG1 could be a potential novel target regulated by STAT3." (PMID 34930899, 2021).
cancer (continued). "The effects of BRG1 on STAT phosphorylation were selective for STAT3, which is consistent with previous findings that silencing BRG1 with shRNA in GBM cancer stem cells resulted in high STAT3 tyrosine phosphorylation but not in the phosphorylation of other STAT proteins." (PMID 33528916, 2021). "In addition, constitutively activated STAT3 promotes the phosphorylation of AKT, which is involved in the proliferation of various cancers." (PMID 34721022, 2021). "The transcription factor Signal transducer and activator of transcription 3 (STAT3) may be regulated by ILK or Akt in inflammatory and cancer contexts." (PMID 34163519, 2021). "Furthermore, studies have shown that cross-talk between the STAT3 and EGFR pathways attenuates the effects of standard therapies and EGFR-targeting treatments on cancer." (PMID 34063134, 2021). "Importantly, one key factor regulating both the maintenance and migration of CSCs is the signal transducer and activator of transcription 3 (STAT3), a factor involved in the development of multiple cancer types." (PMID 34302498, 2021). "The activation of STAT3 and STAT5 by ROS upon cytokine or growth factor treatment can also determine the activation of NADPH oxidase (Nox) in human aortic smooth muscle cells and in cancer cells." (PMID 34642818, 2021). "We analyzed CAF correlations with expression profiles of STAT3/CDK2/4/6 and found that out of the 40 TCGA cancer types analyzed via the TIMER server, CAF and STAT3 expressions were correlated in cohorts of 36 cancers types, while CAF and CDK6 expressions were correlated in 34 cancer types." (PMID 33668805, 2021). "Indeed, it has been recently described that STAT3 phosphorylation at Ser727 and Tyr705 differentially regulates the EMT–MET switch and cancer metastasis." (PMID 34361105, 2021). "In addition, IL-6 treatment induced IGF-1 secretion and IGF-1R expression in NANOG/OCT4-HCC cell lines in a dose-dependent manner, suggesting crosstalk between IL-6/STAT3 signaling and IGF/IGF-1R signaling in HCC cancer stem cells." (PMID 33669204, 2021). "STAT3 activity can inhibit the chemotaxis and activation of CD8+ T cells in melanoma and mediate the differentiation of inhibitory T regulatory (Treg) cells, thus promoting cancer progression." (PMID 33722297, 2021). "Accordingly, cancer cells engineered to overexpress STAT3C remain largely unresponsive to the inhibitory effects of silibinin on key transcriptional and phenotypic targets of STAT3 (e.g., c-myc expression and metabolic reprogramming)." (PMID 34208282, 2021). "Although cancer and cancer stem cells express a high level of TLR9, whether a decrease of STAT3 can occur via reduction of TLR9-mediated signaling by CQ application was not investigated in this paper." (PMID 34299065, 2021). "STAT3 is also required for conversion of non-stem cancer cells into cancer stem-like cells downstream to IL6 receptor." (PMID 33785524, 2021). "Notably, molecular pathways such as nuclear factor erythroid 2–related factor 2 (Nrf2), Wnt, Signal Transducer And Activator Of Transcription 3 (STAT3), and Zinc Finger E-Box Binding Homeobox (ZEB) are a few of the down-stream targets of miRNAs in cancer." (PMID 33670518, 2021). "Moreover, it has been shown that leukemia inhibitory factor (LIF) and the signal transducer and activator of transcription-3 (STAT-3) activates mitogen-activated protein kinase 5 (MEK5), which subsequently activates ERK5 in normal and cancer cells." (PMID 34298754, 2021). "Both STAT3 and EGFR play critical roles in cancer progression." (PMID 34207035, 2021). "It has been noted by other studies that non-canonical activation of STAT3 at S727 is related to certain types of cancers." (PMID 33529218, 2021).
cancer (continued). "Interestingly, STAT3, also a member of the STAT protein family, has been found in many studies to be phosphorylated and mediate drug resistance in cancer therapy." (PMID 33198677, 2020). "However, both high CD44 expression and STAT3 activation in CAFs have been reported to maintain CSC phenotype and promote cancer drug resistance in other cancer types." (PMID 33335857, 2020). "Thus PTPRM suppresses STAT3 signaling in DDIAS-knockdown cells, suggesting that DDIAS promotes the IL-6–mediated STAT3 signaling in malignant cancer cells by inhibiting the PTPRM function." (PMID 31900385, 2020). "Signal transducer and activator of transcription 3 (STAT3), a transcription factor, plays an important role in cancer cell apoptosis, was found to be inhibited by FZKA, GFTN, and much more in the combination group (FZKA combined with GFTN), both at mRNA and protein levels." (PMID 32489321, 2020). "In the present study, pterostilbene resulted in a reduction in the expression levels of phosphorylated STAT3, without affecting the total protein levels of STAT3 in HeLa cancer stem-like cells." (PMID 31935877, 2020). "STAT1, STAT3, and STAT5 were elevated in various human cancer cells." (PMID 32545187, 2020). "IL6 has been shown to mediate its diverse biological functions, such as normal cellular growth and an immune response, through the activation of STAT3, and the dysregulated secretion of IL6 is known to play a crucial role in the pathogenesis of various diseases, including cancer." (PMID 31936675, 2020). "Moreover, LINC00511 was found to interact with a variety of signaling pathways including JAK2/STAT3, Wnt/β-catenin, and PTEN/AKT/FOXO1, in the pathogenesis of cancers." (PMID 32698787, 2020). "The observation that Fusobacteria upregulated STAT3, JAK1, and MYC indicated that Fusobacteria infection might enhance cancer cell survival through modulation of these oncogenes, which are well implicated in pathways that promote tumorigenesis." (PMID 33391626, 2020). "Among the STAT forms, STAT3 and STAT5 have been extensively studied in the cancer context." (PMID 32967366, 2020). "Cell molecules including transcription factors (e.g., NF-κB, STAT3, HIF1α) and cytokines (e.g., IL-6, Cox-2, and TNF-α) coordinate together and lead to the amplification of inflammation and creation of a suitable environment for cancer growth." (PMID 32758196, 2020). "STAT3 correlated with CD68 and CD163, meaning that STAT3 might correlate with M2 macrophage to regulate cancer development." (PMID 32486001, 2020). "TTI-101 blocks the STAT3/CCAAT enhancer-binding protein γ, which directly inhibits the myostatin signaling pathway—the one responsible for muscle protein degradation in both chronic kidney disease and cancer." (PMID 33158194, 2020). "A large-scale cancer cell line screening identified a JAK2-selective inhibitor, AZ960, that blocks STAT3 activation and exhibits higher sensitivity against PDAC cell lines, which supports the utility of therapeutic targeting of JAK2–STAT3 signaling in PDAC." (PMID 32947833, 2020). "In our studies, we found that phosphorylated STAT3 was increased in cancer tissues, as compared with adjacent tissues (data not shown)." (PMID 32491253, 2020). "Additionally, it was also shown that the proteasome inhibitor bortezomib causes an increase in total STAT3, pSTAT3, and cellular STAT3 levels in HNC cells and the combined treatment of GS (natural STAT3 inhibitor) with bortezomib could induce synergistic death of cancer cells." (PMID 36046484, 2020).
cancer (continued). "Not surprisingly, compared with control groups, Stat3 gene depletion in MDA-MB-231 cells led to a dramatic reduction in rhG-CSF-induced cancer cell migration or invasion." (PMID 32242230, 2020). "Furthermore, JAK2/STAT3 inactivation by ALK4 and FRK results in reduced cell survival and aggressiveness of different types of cancer." (PMID 31952344, 2020). "STAT3 and STAT5 factors seem to be the most important agents in light of cancer progression." (PMID 32850012, 2020). "Many reports demonstrated that natural polyphenols including anthocyanin also modulate Akt signaling pathways to inactivate the NF-κB, and STAT3 in cancers, but it is not fully elucidated how these natural polyphenols are suppressing these signaling cascades." (PMID 32784919, 2020). "TLR9 likely promotes stemness in cancer cells via MYD88 and STAT3." (PMID 32843056, 2020). "Further analysis revealed that non-canonical DDR1 signaling through STAT3 is activated during cancer growth and early metastasis." (PMID 33015133, 2020). "These peptides are very selective to inhibit the activities of STAT3 but not the STAT1 or 2 and prevent the growth of cancer cells harbouring the constitutive expression of STAT3." (PMID 36046384, 2020). "The finding of a significant relationship between leptin and TGF-β1 levels in our patients is consistent with previous studies that showed that leptin binds to leptin receptors on the surface of cancer cells, activates JAK/STAT3 signaling, and consequently increases TGF-β expression." (PMID 32968152, 2020). "Cancer cells lose receptor chain binding IL-6, and STAT3 is no longer expressed in cancer cell nests." (PMID 32308553, 2020). "This recently recognized regulation of new oncogenes involved in activating JAK/STAT3/VEGFA, NF-κB, and ERK signaling might provide crucial targets to block the cancer progression." (PMID 31952344, 2020). "Intriguingly, it has been elucidated that STAT3 can be activated by IL-6 through Janus kinase 2 (JAK2), and IL-6/JAK2/STAT3 has been implied as a crucial accelerator for tumorigenesis and EMT in many cancer types, including HCC22." (PMID 31949128, 2020). "STAT3 does not directly induce tumourigenesis but influences the progression of cancer by regulating its downstream target genes." (PMID 32382281, 2020). "The role of STAT2 in cancer is controversial; some reports implicate STAT2 in the carcinogenesis process, proposing that STAT2 can increase IL-6 secretion, and that this in turn activates STAT3, thus promoting tumorigenesis." (PMID 33076315, 2020). "The comparatively modest feedback of agents targeting JAKs from cancer patientsdemonstrates that single pathways possibly will not satisfactory inhibit theactivation of STAT-3." (PMID 32167126, 2020). "NANOGP8 is expressed in many cancers and its ability to substitute for NANOG in reprograming activity, prompted us to analyze the relative contribution of NANOG and NANOGP8 in STAT3-dependent upregulation of total NANOG during our reprogramming procedure." (PMID 32580970, 2020). "Many studies have reported that Eph receptor’s forward signaling could activate Src, RHOA, RAC1, CDC42, STAT3 (signal transducer and activator of transcription 3), and PIK3/Akt in a variety of tumors which promote cancer-cell migration and invasion." (PMID 31893311, 2020). "In various cancers, curcumin has been shown to inhibit growth and proliferation of cancer cells by targeting various survival pathways, including JAK/STAT3, PI3-kinase/AKT, Transforming growth factor beta (TGF-β), Epidermal Growth Factor Receptor (EFGR), and NF-кB." (PMID 31936675, 2020). "The sphere formation assay found CSC proliferation to be significantly decreased in NONO-silenced cancer cells; this was reversed by reintroducing STAT3 and reduced the expression of CSC markers by NONO-silencing was recovered by reintroducing STAT3." (PMID 32724453, 2020).
cancer (continued). "Subsequently, both nontyrosine and tyrosine phosphorylated STAT3 perform significant roles in cancer cells, and this knowledge can be utilized to develop potential anticancer agents." (PMID 32545187, 2020). "Neutrophils marker genes C-C motif chemokine receptor 7 (CCR7) and CD11b, were favorably linked to STAT3 in cancer, except for CCR7 showing a negative correlation with STAT3 in BLCA." (PMID 32486001, 2020). "Finally, miR-486-5p also promote the expression of five genes with promoting cancer roles: KDM4C, PPARD, KLF4, STAT3, and TCF7l2." (PMID 33227890, 2020). "STAT-3 is activated by several types ofinflammatory cytokines, carcinogens, viruses, growth factors, and oncogenes.Thus, the STAT3 pathway is a potential target for cancer therapeutics." (PMID 32167126, 2020). "Finally p‐STAT3, Mcm2, and MSR1 were used to construct the model for predicting cancers in the repeat biopsy cohort." (PMID 32860339, 2020). "Notably, miRs are able to target endogenous inhibitors of the STAT3 signaling pathway, such as PIAS3, in cancer cells." (PMID 32545648, 2020). "Arnold found that radiation expanded cancer stem cell populations and can induce stemness in nonstem cells in a STAT3-dependent manner." (PMID 32733808, 2020). "transcription factors AP-1, NF-κB, STAT3, GR, PR, and FOXA1/2 are inducible in nature and their aberrant expression and constitutive activation play an independent role in carcinogenic inflammation, transformation and maintenance of cancer stemness." (PMID 33344262, 2020). "In TME, IL-6 could be produced by inflammatory cells 9, cancer cells 10, and MSCs 10-12, while hyperactivation of IL-6/JAK/STAT3 signaling pathways within a TME contributes to aggressiveness and progression of cancer through multifaced mechanisms." (PMID 32127934, 2020). "IL6/STAT3/TWIST signaling pathway activation mediates esophageal squamous carcinoma EMT, whereas inactivation of STAT3 by an IL-6 inhibitor or siRNA-mediated downregulation of Twist enhances cancer cell apoptosis and reverses radiation-induced EMT." (PMID 32872659, 2020). "IL-6/JAK/STAT3 and TGF-β signaling also participated in cancer inflammation and immunity." (PMID 33194678, 2020). "In addition, carcinogenic HPVs also affect additional cancer‐related pathways, including the PI3K/AKT, signal transducer and activator of transcription 3 (STAT3), and metabolism pathways." (PMID 32491253, 2020). "In addition, we also explored the role of IL6 in the stimulation of STAT3 and in the growth and proliferation of PTC cancer cells." (PMID 31936675, 2020). "Together, these studies show that inhibition of STAT3 may be a potential therapeutic strategy in both HPV infection and HPV+ cancers." (PMID 32899142, 2020). "Our results confirmed that the compounds significantly decreased the expression levels of phosphorylated STAT3, without inhibiting the total protein levels of STAT3 in HeLa cancer stem-like cells." (PMID 31935877, 2020). "Stattic and BP-1-102, which are nonpeptidic small-molecule inhibitors of Stat3, have been widely used in various studies, particularly in cancer research." (PMID 32059373, 2020). "Taking into account the widespread recognized control of STAT3 signaling on both normal and cancer cell proliferation, a possible modulation by treatments of this signaling in both Mz-ChA-1 cancer and H69 noncancerous cholangiocytes was also assessed." (PMID 32252311, 2020). "Beyond canonical tyrosine 705 phosphorylation in Janus kinase-STAT3 (JAK-STAT3) signalling, it directs and promotes cancer growth and metastasis through non-canonical signaling by serine phosphorylation at position 727 as well as in its unphosphorylated state." (PMID 32331320, 2020).